GP2 (glycoprotein 2)
Diseases named in the same sentence as GP2 in open-access papers (continued):
Sharing a sentence is not in itself a finding about the gene and the disease.
colitis (7 papers, 2021 to 2024). Inflammation of the colon. "Patients suffering from IBD show higher fecal GP2 levels, whereas GP2 deficient colitis mice exhibit a phenotype characterized by increased intestinal inflammation and epithelial attachment of E. coli." (PMID 39427219, 2024). "Pancreas-specific GP2-deficient colitis mice have a larger mucosal E. coli population than the intact mice, indicating that the digestive-tract GP2 binds the commensal E. coli, preventing the epithelial attachment and penetration by this pathogen." (PMID 35752737, 2022). "Indeed, it has been demonstrated that GP2-deficient colitis mice present a more severe intestinal inflammation and an enhanced E. coli population than healthy mice, proving the role of GP2 in preventing E. Coli mucosal attachment and penetration." (PMID 34573354, 2021). "Consequently, GP2 deficiency may exacerbate the severity of colitis, considering the well-established association between increased E. coli levels and colonic inflammation." (PMID 38170255, 2024). "Furthermore, pancreas-specific GP2-deficient colitis mice have more severe intestinal inflammation and a larger mucosal E. coli population than do intact mice, indicating that digestive-tract GP2 binds commensal E. coli, preventing epithelial attachment and penetration." (PMID 33594081, 2021). "Thus, the reduction of GP2 expression and/or neutralization of its function may increase the risk of developing colitis." (PMID 33594081, 2021). "In a mouse model of dextran sodium sulfate (DSS)-induced colitis, pancreatic GP2 levels were elevated." (PMID 38170255, 2024). "The increased amounts of GP2 in the pancreatic juice and intestinal lumen in colitis mice suggested increased granular release of GP2 from pancreatic acinar cells." (PMID 33594081, 2021). "In a chemically induced colitis in mice, an increase of GP2 expression in the pancreas has been observed, which has been an effect of enhanced production of pro-inflammatory cytokines such as TNF." (PMID 34064706, 2021). "Meanwhile, DSS-induced colitis promotes the expression of glycoprotein 2 (GP2), a specific marker of M cells, in the colon of wild-type (WT) mice but not in MyD88−/− mice." (PMID 35051090, 2021). "Next, to examine GP2 expression in colitis, we compared gene expressions between intact mice and mice in which colitis was induced by administration of dextran sodium sulfate (DSS)." (PMID 33594081, 2021). "Here, we show that secretion of luminal glycoprotein 2 (GP2) from pancreatic acinar cells is induced in a TNF–dependent manner in mice with chemically induced colitis." (PMID 33594081, 2021). "Flow cytometric analysis revealed that in Gp2–/– mice about 25% of the fecal bacteria were bound to GP2, and this was further increased to about 36% in colitis mice." (PMID 33594081, 2021). "The development of colitis results in an increased GP2-bound bacteria ratio compared with the steady state, contributing to worsening of inflammation." (PMID 33594081, 2021). "Given our present data showing elevated production of GP2 by pancreatic acinar cells during colitis, we next examined the pancreas–colon axis and the mechanisms underlying how colonic inflammation leads to increased synthesis of pancreatic GP2." (PMID 33594081, 2021). "The colitis promotes the transcription of some genes related to M cell differentiation and the expression of GP2." (PMID 35051090, 2021). "Colon loops from Gp2–/– mice with colitis received E. coli S-17-GFP showing mucosal invasion of bacteria with green fluorescent signals." (PMID 33594081, 2021). "By contrast, an increase of GP2 expression in the pancreas has been observed in a chemically induced colitis in mice, as a consequence of the production of pro-inflammatory cytokines such as TNF." (PMID 34573354, 2021). "We found that the ratio of GP2-bound bacteria was significantly increased in colitis, even when abundant amounts of GP2 were secreted by the pancreas." (PMID 33594081, 2021).
colitis (continued). "In addition to assessing the impact of GP2 on the diversity of gut microbial species, we explored whether GP2 deficiency might lead to an increased bacterial load in the intestinal mucosa, which is particularly relevant since elevated mucosal bacterial numbers are often associated with colitis." (PMID 38170255, 2024). "Nevertheless, based on our observations, we suggest that in cases of colitis, the increase in luminal GP2 may be attributed to de novo synthesis." (PMID 38170255, 2024). "Notably, our recent study provides compelling evidence of increased pancreatic GP2 expression in individuals with colitis." (PMID 38170255, 2024). "Even during colitis when pancreatic GP2 secretion increases, there are still more bacteria that remain unbound to GP2, which may contribute to the worsening of the inflammation." (PMID 38170255, 2024). "In addition, histological and flow cytometry analyses revealed marked neutrophil infiltration and bacterial invasion in the TNBS-colitis Gp2–/– mice compared with in the TNBS-colitis WT mice." (PMID 33594081, 2021). "In summary, we found that pancreatic GP2 contributed to the prevention of bacterial adhesion to the intestinal mucosa, indicating that GP2 acts as a first line of defense in controlling the severity of colitis." (PMID 33594081, 2021). "Importantly, as in the DSS-colitis model, the production of pancreatic GP2 was markedly upregulated in the TNBS-colitis WT mice." (PMID 33594081, 2021). "Together, these results suggest that the main source of GP2 is the pancreas, not M cells, and that GP2 limits the severity of colitis-associated intestinal inflammation." (PMID 33594081, 2021). "However, the expression levels of genes encoding enzymes that contribute to the cleavage of the GPI anchor of GP2 from the granule membrane (e.g., phospholipases, carboxypeptidase, and trypsin) were unaltered in mice with colitis 36,37." (PMID 33594081, 2021). "Our present results indicate that systemic antibodies to commensal bacteria (e.g., E. coli) are induced during colitis and that translocated GP2-conjugated bacteria might act as immunopotentiators for the induction of an autoimmune response to GP2." (PMID 33594081, 2021). "Therefore, we predicted that together with the increase of GP2 expression, GP2-secretory pathways would also be altered in colitis." (PMID 33594081, 2021). "It is possible that by disrupting the mucosal barrier by inflammation, different species of bacteria bound to GP2 may translocate and then induce the production of GP2 autoantibodies in colitis." (PMID 34064706, 2021). "Indeed, serum Ig levels against E. coli revealed that among Ig class, especially serum IgA against E. coli was significantly increased in Gp2–/– colitis mice, indicating that immunological responses to infiltrated or disseminated E. coli occurred in the systemic compartment." (PMID 33594081, 2021). "Further investigations revealed that the increased expression of GP2 in the pancreas was closely correlated with tumor necrosis factor-α (TNF-α), an inflammatory agent that is markedly elevated in cases of colitis." (PMID 38170255, 2024). "In addition, we found that the number of GP2-bound bacteria was further increased by incubation with additional rGP2, indicating that the fecal bacterial population was not saturated with GP2, even though the production of pancreatic GP2 was increased during colitis." (PMID 33594081, 2021). "To further examine the involvement of TNF in GP2 production, we administrated TNF-neutralizing or control antibodies to DSS-colitis mice during the colitis induction period." (PMID 33594081, 2021). "Even though we did not purify antibodies to GP2 from the luminal contents of mice with colitis, our findings revealed that pre-incubation with luminal contents containing anti-GP2 autoantibodies resulted in a reduction of GP2 binding to E. coli." (PMID 33594081, 2021).
colitis (continued). "Here, the authors show pancreatic GP-2 is the source of the intestine’s luminal GP-2 that binds bacteria and prevents them from attaching to the epithelium, also limiting pathology in a DSS colitis mouse model." (PMID 33594081, 2021). "A lack of pancreatic GP2 resulted in greater bacterial invasion in the large intestine in mice with colitis compared with in intact mice." (PMID 33594081, 2021). "When the concentrations of unbound GP2 were measured and compared between WT mice with and without colitis, the levels of unbound GP2 were comparable between the two groups." (PMID 33594081, 2021). "In addition, the concentrations of GP2 in pancreatic juice and luminal washout were increased in DSS-colitis mice compared with intact mice, indicating increased GP2 production under the inflammatory condition." (PMID 33594081, 2021). "However, in WT mice with colitis, even without the addition of GP2, E. coli were detected, indicating that the GP2-bound E. coli population was increased during colitis." (PMID 33594081, 2021).
diabetes (7 papers, 2014 to 2024). "The db/db + mSTZ state had higher activity of multiple GPs that contained known diabetes markers or were associated with ER stress (GP2, GP3 and GP4) and cell state mSTZ had higher activity of GPs associated with immaturity (GP8 and GP23)." (PMID 37697055, 2023). "After adjusting for age, BMI, hypertension, diabetes and dyslipidemia, the relative abundance of GP2, GP4, GP6, and GP10 of LN among SLE women were higher, while the relative abundance of GP8, GP14, GP16, GP18, and GP23 were reduced." (PMID 37809087, 2023). "Due to the high, close to exclusive, expression of GP2 in the islets of Langerhans, according to the gene atlas of the mouse and human protein encoding transcripts, accessed via BioGPS.org, evaluation of genetic variants in or near this gene could be highly relevant to diabetes research." (PMID 24695378, 2014). "Our findings from association analysis of diabetes-related biomedical indexes indicated that although NUS1 and GP2 both contribute to the risk of GDM, they might be involved in different mechanisms of GDM." (PMID 34326813, 2021).
primary sclerosing cholangitis (7 papers, 2018 to 2024). "Positive and negative (italic) significant associations of IgA and IgG against GP2 isoforms 1 (aGP21) to 4 (aGP24) with the clinical phenotype in 212 patients with primary sclerosing cholangitis (PSC) by Fisher's exact test." (PMID 30233574, 2018). "Furthermore, in primary sclerosing cholangitis, an autoimmune liver disease associated with a specific change of the gut microbiota, the occurrence of GP2 IgA is a predictor of disease severity and cholangiocarcinogenesis." (PMID 39427219, 2024). "In addition to pancreatic diseases, GP2 has been linked to multiple disease phenotypes, including CD, ulcerative colitis (UC), and primary sclerosing cholangitis." (PMID 34861888, 2021). "GP2 was identified as an autoantigenic target in Crohn’s disease (CD) and primary sclerosing cholangitis." (PMID 34861888, 2021). "Frequency of IgA and IgG against GP2 isoforms 1 (aGP21) to 4 (aGP24) detected by indirect immunofluorescence assay on stabile isoform-transduced HEp2 cells in 212 patients with primary sclerosing cholangitis (PSC) from different hospitals and 145 controls." (PMID 30233574, 2018). "Notably, CD patients with pouchitis exhibit elevated levels of anti-GP2 IgA, and elevated levels of anti-GP2 IgA autoantibodies have also been detected in a minority of UC patients, particularly those with primary sclerosing cholangitis (PSC) as an extraintestinal manifestation." (PMID 38170255, 2024). "IgA type PABs were more prevalent in patients with primary sclerosing cholangitis (37.5% vs. 4.7% for anti-CUZD1 and 12.5% vs. 0% for anti-GP2, p<0." (PMID 29590158, 2018).
ulcerative colitis (6 papers, 2012 to 2018). An inflammatory bowel disease involving the mucosal surface of the large intestine and rectum. "The unexpectedly high prevalence of anti-CUZD1 and anti-GP2 antibodies in patients with ulcerative colitis warrants further investigations, as PABs are only found in less than 8% of patients with this disease." (PMID 23710207, 2013). "Anti-GP2 antibodies were tested in 225 CDs, including 45 patients with colonic location (L2), 45 with terminal ileum (L1) and 135 with ileocolonic involvement; 225 patients with ulcerative colitis (UC) were also tested." (PMID 23118780, 2012). "Anti-GP2 and anti-Saccharomyces cerevisiae (ASCA) IgA and IgG were detected by ELISA employing recombinant human GP2 and phosphopeptidomannan, respectively and PAB by indirect immunofluorescence (IIF) in 271 sera, 169 with CD and 102 with ulcerative colitis (UC)." (PMID 22866900, 2012). "These authors did not provide data for individual reactivity to CUZD1 and GP2, but their overall data indicated the presence of PABs against the two antigens in 35.9% of patients with CD, 24.5% of patients with ulcerative colitis, and in none of the pediatric controls." (PMID 23710207, 2013).
viral infection (6 papers, 2010 to 2025). "Alternatively, neutralizing epitopes have also been shown in GP2, 3, and 4, with which another complex is formed as an essential player in receptor binding and viral infection." (PMID 40559814, 2025). "The envelope glycoproteins GP1 and GP2 of Lassa virus (LASV) bind to the host cell receptors to mediate viral infection." (PMID 31456769, 2019). "Alternatively, neutralizing epitopes have also been shown in GP2, GP3, and GP4, with another complex formed as an essential factor in receptor binding and viral infection." (PMID 40559814, 2025).
pancreatic cancer (5 papers, 2019 to 2024). "A search of the GWAS catalog revealed that GP2 variants are associated with body mass index (BMI), type 1 and 2 diabetes, acute myeloid leukemia, and sleep quality in addition to pancreatic cancer." (PMID 34861888, 2021). "In 2020, we discovered glycoprotein 2 (GP2) variants associated with pancreatic cancer susceptibility in a genome-wide association study involving the Japanese population." (PMID 34861888, 2021). "We identified the strongest GWAS “hit” for pancreatic cancer in the GP2 gene, where a total of 10 variants were significantly (p<5 × 10−8) associated with the risk." (PMID 34861888, 2021). "Perhaps coincidently, in 2020, we discovered GP2 variants associated with pancreatic cancer susceptibility in a genome-wide association study (GWAS) involving the Japanese population." (PMID 34861888, 2021). "In 2020, we identified GP2 variants associated with pancreatic cancer risk in a GWAS involving the Japanese population, providing further evidence that the leading missense variant in the GP2 gene, rs78193826, is a functional, Asian-specific variant." (PMID 34861888, 2021). "In conclusion, our GWAS meta-analysis identified a risk locus at chromosome 16p12.3 within the GP2 gene for pancreatic cancer in populations of East Asian ancestry." (PMID 32581250, 2020). "Further fine mapping and functional characterization are needed to elucidate the associations of common GP2 gene variants with pancreatic cancer susceptibility." (PMID 32581250, 2020). "Here the authors identify GP2 gene variants associated with pancreatic cancer susceptibility in populations of East Asian ancestry." (PMID 32581250, 2020). "Together, these findings indicate that GP2 gene variants are probably associated with pancreatic cancer susceptibility in populations of East Asian ancestry." (PMID 32581250, 2020). "Perhaps coincidently, the lead variant (rs117267808) in the GP2 gene identified in the latest GWAS meta-analysis of T2D in the Japanese population was also identified in our GWAS meta-analysis of pancreatic cancer." (PMID 32581250, 2020). "Associations between selected GP2 gene variants and pancreatic cancer are replicated in 10,822 additional cases and controls of East Asian origin." (PMID 32581250, 2020). "We explored the functional impact of the identified coding variant rs78193826 in the GP2-expressing pancreatic cancer cell line PaTu 8988s." (PMID 32581250, 2020). "Genetic variations in the GP2 gene have been linked to several phenotypes in addition to pancreatic cancer." (PMID 32581250, 2020). "It was not until 2020 that a groundbreaking study based on a meta-analysis of three genome-wide association study (GWAS) datasets comprising 2039 pancreatic cancer patients and 32,592 controls from Japan confirmed the relatively pivotal role of GP2 gene variants in pancreatic cancer." (PMID 38170255, 2024). "Notably, the GP2 variant rs117267808, which is in complete linkage disequilibrium (r2=1 according to 1000 genomes phase 3 JPT) with the GP2 lead variant rs78193826, was associated with both pancreatic cancer and type 2 diabetes in the Japanese population." (PMID 34861888, 2021). "We hope that its robust genetic associations with pancreatic cancer, coupled with its emerging role in gastrointestinal mucosal immunity, will spur renewed research interest in GP2, which has been understudied over the past 30 years compared with its paralog uromodulin (UMOD)." (PMID 34861888, 2021). "Several lines of evidence indicate that rs78193826, which lies within the GP2 gene on 16p12.3, may be associated with pancreatic cancer risk." (PMID 32581250, 2020). "In particular, the biological functions of GP2 in the development of pancreatic diseases, including pancreatitis and pancreatic cancer, remain poorly understood." (PMID 34861888, 2021). "The ROC curve further demonstrates the ineffectiveness of GPC1 EVs and GPC1+GP2 EVs in discerning BPD from pancreatic cancer." (PMID 30800217, 2019).
pancreatic cancer (continued). "The best cut-off for the diagnosis of pancreatic cancer using the GPC1+GP2 EV test was greater than 780 EVs per microliter, yielding a sensitivity and specificity of 23.33% and 90.0% respectively." (PMID 30800217, 2019). "We tested the utility of a blood test enumerating EVs positive for the pancreas-specific marker Glycoprotein 2 (GP2) and the putative pancreatic cancer marker Glypican-1 (GPC1) in patients with PDAC." (PMID 30800217, 2019). "Individuals carrying a missense coding variant (rs78193826) in the GP2 gene resulting in a p.V432M substitution had an approximately 1.5-fold higher risk of developing pancreatic cancer than those without this variant." (PMID 34861888, 2021). "Survival analysis of 176 pancreatic cancer patients included in the TCGA database showed no significant survival differences between the groups with high and low GP2 mRNA levels (log-rank P value=0.28)." (PMID 34861888, 2021). "Hence, enumeration of GPC1-positive EVs, solely or in conjunction with GP2, was unable to effectively distinguish between BPD and pancreatic cancer." (PMID 30800217, 2019). "GP2 has been detected in the blood of patients affected by various pancreatic diseases including both pancreatic cancer and pancreatitis, thus we sought to enumerate GPC1-GP2 dual positive EVs in patient plasma samples representing various stages of pancreatic cancer development." (PMID 30800217, 2019). "Whether through the analysis of GPC1 alone or in conjunction with GP2, target EV counts between all three groups did not significantly differ and thus was not informative regarding pancreatic cancer status." (PMID 30800217, 2019). "The rarity of GPC1-positive EVs and lack of consistent co-occurrence with GP2 in pancreatic cancer patients challenge the notion that GPC1 present on EVs is exclusively found and derived from cancer of the pancreas (given that patients are unaffected by other cancers)." (PMID 30800217, 2019). "A gating of only EVs between 110-150nm meant to enumerate GPC1+ve, GP2+ve or GPC2 and GP2 dual positive exosomes (small EVs) also failed to distinguish between patients with BPD and pancreatic cancer." (PMID 30800217, 2019).